BCL3 (BCL3 transcription coactivator)
Diseases named in the same sentence as BCL3 in open-access papers (continued):
Sharing a sentence is not in itself a finding about the gene and the disease.
rheumatoid arthritis (4 papers, 2016 to 2022). A chronic, systemic autoimmune disorder characterized by inflammation in the synovial membranes and articular surfaces. "This cell-type specific effect was corroborated by work in CD4+ cells using a rheumatoid arthritis model, which showed overexpression of Bcl-3 in these cells was implicated in the pathogenesis of rheumatoid arthritis." (PMID 31930327, 2020). "We highlight six tocilizumab responsive genes (ARID5A, BCL3, PIM1, SOCS3, BATF, MYC) that are associated with IL-6 pathway and known to be perturbed by tocilizumab treatment in rheumatoid arthritis patients." (PMID 35064122, 2022).
adenoma (3 papers, 2016 to 2021). A neoplasm arising from the epithelium. "To examine the role of BCL-3 in Wnt/β-catenin signalling, we first screened a panel of human adenoma- and carcinoma-derived cell lines for expression of BCL-3 and β-catenin." (PMID 30792270, 2019). "Results show that both adenoma- and carcinoma-derived cell lines express β-catenin and BCL-3 protein, although there is an apparent inverse correlation between β-catenin and BCL-3 protein levels (those cells with lowest β-catenin generally having higher levels of BCL-3)." (PMID 30792270, 2019). "As we have shown that BCL-3 acts as a survival factor in the adenoma as well as carcinoma-derived cells, it is interesting to speculate that the ability to repress BCL-3 may contribute to the effectiveness of these NSAIDs in preventing tumorigenesis." (PMID 26033966, 2016). "The authors also found seven markers specifically able to differentiate between large adenomas and CRC (BCL3, PTGES, PPARG, MMP11, IL8, TNFSF13B, CXCR3)." (PMID 33806465, 2021). "However, it is important to stress that in the current study AKT activation by BCL-3 was clearly detected in more than one carcinoma cell line (we have detected BCL-3-induced AKT activation in SW480, SW620, HCA7, HT29 and HCT116 cells) as well as RG/C2 adenoma-derived cells." (PMID 26033966, 2016).
Autoimmunity (3 papers, 2017 to 2025). The occurrence of an immune reaction against the organism's own cells or tissues. "Even though not related to autoimmunity, Bcl3 deficiency also resulted in resistance to skeletal muscle atrophy, a phenomenon that is phenotypically mimicked in p105/p50 (Nfkb1) knockout mice." (PMID 40359334, 2025). "Although Bcl3‐deficient mice do not suffer from spontaneous autoimmunity, they are more susceptible to streptozotocin‐induced type 1 diabetes." (PMID 40359334, 2025). "Global Bcl3 knockout mice also do not show signs of autoimmunity, whereas the combined absence of Bcl3 and Nfkb2 results in the loss of central tolerance and autoimmunity." (PMID 40359334, 2025). "We found that Bcl-3 has a metabolic regulatory effect on autoimmunity." (PMID 36159779, 2022). "Bcl-3 modulates effector T cell responses, but the importance of Bcl-3 in T regulatory cells and autoimmunity is not clear." (PMID 28452361, 2017).
Cachexia (3 papers, 2004 to 2022). Severe weight loss, wasting of muscle, loss of appetite, and general debility related to a chronic disease. "NF-κB was shown to target Trim63 in skeletal muscle in cachexia and the present work supports these data in atrophying muscle due to unloading, although we show a role for p50 and Bcl-3 rather than involvement of p65." (PMID 21249144, 2011). "Thus, hind-limb unloading, a model of disuse atrophy, resulted in a 10-fold increase in the activity of a transfected NF-κB-dependent reporter, but this involved p50, c-Rel and Bcl-3 and not activation of p65 or I-κB, and is thus distinct from cachexia." (PMID 15477867, 2004). "Of the six proteins that showed significant differences between the patients with and without cachexia, three were lower (CNPD1, APOA4, DACH1) while three were higher (BCL3 NARS2, ATP13A4) in cachexia." (PMID 36080280, 2022).
Crohn disease (3 papers, 2014 to 2022). A gastrointestinal disorder characterized by chronic inflammation involving all layers of the intestinal wall, noncaseating granulomas affecting the intestinal wall and regional lymph nodes, and transmural fibrosis. "A 2010 study identified single-nucleotide polymorphisms in the BCL3 gene, which predicted reduced Bcl-3 protein expression, as a likely risk factor for Crohn’s disease." (PMID 27023613, 2016). "Reduced Bcl3 expression has been associated with Crohn’s disease which is known to be mediated by Th17 chronic expansion." (PMID 25495206, 2014). "In the original GWAS and in a combined analysis of two independent Dutch replication cohorts, two novel potential risk genes for Crohn’s disease were identified: UBE2L3 and BCL3." (PMID 35265070, 2022). "A more recent report, however, demonstrates that patients with both Crohn’s disease and ulcerative colitis have elevated expression of BCL3 compared to healthy individuals." (PMID 27023613, 2016).
experimental autoimmune encephalomyelitis (3 papers, 2021 to 2022). An autoimmune demyelinating disease of the central nervous system that is produced experimentally in animals by the injection of homogenized brain or spinal cord in Freund's adjuvant. "It is evident from the results that Bcl-3 regulates lactate synthesis by interacting with Raptor, thus regulating the differentiation of Th17 cells that alleviated experimental autoimmune encephalomyelitis." (PMID 36159779, 2022). "Bcl-3-depleted mice are unable to develop experimental autoimmune encephalomyelitis." (PMID 36159779, 2022).
lupus (3 papers, 2022 to 2025). "Also, in the context of systemic lupus erythematosus (SLE)–like disease, Bcl‐3 was shown to play a protective role, since Bcl3‐deficient mice carrying the lpr mutation developed a more severe SLE–like inflammatory phenotype than control lpr mice." (PMID 40359334, 2025).
lymphoproliferative disorder (3 papers, 2016 to 2024). "The putative oncogenic role of BCL3 is supported by an Eμ-BCL3 transgenic mouse model, which exhibits a lymphoproliferative disorder." (PMID 29587428, 2018). "Bcl-3 over-expression detrimentally alters the composition of both the B and T cell compartments, with animals suffering lymphoproliferative disorders." (PMID 27023613, 2016).
metastatic tumor (3 papers, 2017 to 2024). "In mice models, knockdown of Bcl3 in ErbB2 positive BC resulted in decreased cell motility and metastatic progression without affecting primary tumor growth; however, resulted in severe reduction of lung metastatic tumors." (PMID 29287594, 2017).
Splenomegaly (3 papers, 2013 to 2025). Abnormal increased size of the spleen. "In contrast, the Eμ‐Bcl3 transgenic mice, in which Bcl‐3 is overexpressed in B and T cells, display splenomegaly and an accumulation of mature B‐cells in secondary lymphoid organs." (PMID 40359334, 2025). "Eμ-BCL-3 transgenic mice display splenomegaly, lymphadenopathy and elevated levels of mature B cells in the secondary lymphoid organs, the peritoneal cavity and the bone marrow, suggesting that BCL-3 overexpression renders B cells into a state of hyperactivation." (PMID 23578005, 2013). "In addition, there is an upregulation of BCL-3 in lymphoid malignancy, and BCL-3-transgenic mice show splenomegaly and an accumulation of mature B cells in lymph nodes." (PMID 36982231, 2023).
squamous cell carcinoma (3 papers, 2011 to 2024). A carcinoma arising from squamous epithelial cells. "In transgenic animals, sustained Bcl-3 nuclear translocation leads to the development of skin papilloma or squamous cell carcinoma by augmentation of p50/p52-related NF-κB binding in mouse keratinocytes." (PMID 38238702, 2024). "Finally, the role of Bcl-3 in skin/adnexal tumorigenesis is also supported by a mouse model of skin carcinogenesis in which Bcl-3 is strongly overexpressed in late papillomas and squamous cell carcinoma." (PMID 22195643, 2011). "Thus, the enhanced proportion of squamous carcinomas in bcl-3−/− mice might have been due to increased numbers of cells of origin." (PMID 35681213, 2022). "We found that absence of Bcl-3 results in tumors with higher proportions of squamous carcinoma or anaplastic sarcomatoid lesions relative to the microacinar basaloid adenocarcinomas." (PMID 35681213, 2022).
viral infection (3 papers, 2019 to 2025). "Zebrafish with Bcl3 deficiency further showed enhanced immune responses and increased susceptibility to both bacterial and viral infections, resulting in significantly elevated levels of pro-inflammatory cytokines il1b, il6, il8, and tnfa." (PMID 41439955, 2025). "Zebrafish with Bcl3 deficiency exhibited growth retardation, reduced survival, compromised integrity of immune organs, enhanced pro-inflammatory responses, and increased susceptibility to both bacterial and viral infections." (PMID 41439955, 2025). "Together, our results establish Bcl-3 as an autonomous determinant of memory/terminal effector cell balance during CD8+ T cell differentiation in response to acute viral infection." (PMID 33508001, 2021). "Here we show a critical cell-autonomous role for Bcl-3, an atypical member of the IκB family, in the regulation of CD8+ T cell differentiation/memory formation during acute viral infection with lymphocytic choriomeningitis virus." (PMID 33508001, 2021). "In agreement with the role of H3K79 methylation in viral infection, alterations in RUBCN, TRIM25 and BCL3 gene expression in DOT1L down-regulated cells were found." (PMID 31727944, 2019). "Despite these advances in knowledge, the role played by Bcl-3 during one of the most important biologic functions of T cells, control of viral infection, has not been previously investigated." (PMID 33508001, 2021).
acute liver failure (2 papers, 2022 to 2025). Rapid deterioration of liver function causing encephalopathy and coagulopathy. "In conclusion, our study identifies a pivotal role for Bcl3 in the early stages of APAP-induced acute liver failure." (PMID 40015625, 2025).
acute myeloblastic leukemia (2 papers, 2019 to 2020). "In the correlation analysis of BCL3 expression with clinic-pathologic features, the M2 subtype of acute myeloblastic leukemia with maturation had a significantly higher frequency of low BCL3 expression than other subtypes." (PMID 30357752, 2019).
Anxiety (2 papers, 2020 to 2021). Intense feelings of nervousness, tension, or panic often arise in response to interpersonal stresses. "SUZ12, TCF7L1, and BCL3 could bind to the CNR1 promoter region to regulate the expression of CNR1, which was associated with anxiety and chronic pain." (PMID 32434423, 2020). "Interestingly, among the anxiety- and depression-related DEGs, we found the upregulation of Bcl3, C3, Gpat3, and Tnf in the AMY as well as the increased expression of Crhr2, Nant, Sar1a, and Tgif1 and the decreased expression of Ier2, Il12a, Nrep, and Tnfrsf25 in the ACC." (PMID 33898422, 2021).
atherosclerosis (2 papers, 2022). A disease characterized by the build-up of fatty material and calcium deposition in the arterial wall resulting in partial or complete occlusion of the arterial lumen. "Finally, BCL3, the gene associated with the third most DM promoter, is known to play a role in atherosclerosis, with atherosclerosis-like lesions potentially leading to AS." (PMID 35463757, 2022).
Atrophy (2 papers, 2011 to 2012). Any weakening or degeneration, especially through lack of use. "From the ChIP-Array results we have found 5 new candidate transcription factors, most notably including Max, that appear to extend the Bcl-3 gene activation network in muscle atrophy." (PMID 23251550, 2012). "To identify direct targets of p50 and Bcl-3 we performed chromatin immunoprecipitation of selected genes previously shown to have roles in atrophy." (PMID 21249144, 2011).
B-cell neoplasm (2 papers, 2015 to 2026). A group of heterogeneous lymphoid tumors generally expressing one or more B-cell antigens or representing malignant transformations of B-lymphocytes. "Aiming at comprehensive molecular characterization of IGH::BCL3-positive B-cell neoplasms, we here investigated samples from 84 patients using fluorescence in situ hybridization (FISH), whole-genome and targeted sequencing, and DNA methylation analyses." (PMID 42064384, 2026). "Our findings highlight the genetic and epigenetic homogeneity of IGH::BCL3-translocated CLL samples and their differences from other types of CLL, suggesting IGH::BCL3 leukemic B-cell neoplasms to be a biological distinct type within the spectrum of mature lymphatic leukemia/CLL." (PMID 42064384, 2026).
esophageal squamous cell carcinoma (2 papers, 2021 to 2024). Esophageal squamous cell carcinoma (ESCC) is a type of esophageal carcinoma (EC) that can affect any part of the esophagus, but is usually located in the upper or middle third. "Here, we show for the first time BCL3 upregulation in esophageal squamous cell carcinoma and its high potential as a diagnostic biomarker, since it precedes the first histopathological alterations." (PMID 34422669, 2021).
head and neck cancer (2 papers, 2021 to 2025). A primary or metastatic malignant neoplasm affecting the head and neck. "Research indicates that BCL3 generates immunosuppressive effects, aligning with studies showing that advanced disease stages correlate with poor clinical outcomes in head and neck cancers." (PMID 40486320, 2025). "Furthermore, our study highlights a set of data to support the use of BCL3 mRNA expression as a biomarker of ESCC detection, suggesting further studies should be performed to corroborate these findings in high-risk groups for ESCC development, as head and neck cancer patients." (PMID 34422669, 2021).
Hodgkins lymphoma (2 papers, 2019 to 2023). A heterogeneous group of malignant lymphoid neoplasms of B-cell origin characterized histologically by the presence of Hodgkin and Reed-Sternberg (HRS) cells in the vast majority of cases. "Nevertheless, latter research has shown that BCL3 rearrangement is recurrent in other hematological malignancies, such as T cell lymphoma, Burlitt-like lymphoma, Hodgkin lymphoma." (PMID 30357752, 2019). "This analysis highlighted that many KEGG Hodgkin lymphoma pathway genes are jointly induced by TES1 and TES2 signaling in LCLs, including CCL22, BCL3, cRel, IRF4, STAT3, STAT6, and CD70, each of which has prominent roles in Hodgkin lymphoma pathogenesis." (PMID 38009935, 2023).
liver disease (2 papers, 2022). "Taken together, these findings suggest that Bcl-3 could serve as a potential therapeutic target for liver diseases caused by TNF-induced apoptosis." (PMID 34853447, 2022). "By revealing this novel role of Bcl-3 in regulating TNF-induced hepatic cell death, this study provides a potential therapeutic target for liver diseases caused by TNF-related apoptosis." (PMID 34853447, 2022). "Related to these pleiotropic functions of Bcl-3, we developed a transgenic mouse model overexpressing Bcl-3 selectively in hepatocytes (Bcl-3Hep) to study its abundant role in liver disease and employed two established models of ALF." (PMID 35641486, 2022). "In this study we found that Bcl-3 promotes TNF-induced hepatocyte apoptosis by enhanced RIP1 deubiquitination, providing a novel Bcl-3-targeted strategy for various liver diseases." (PMID 34853447, 2022). "In this study, we showed an NF-κB-independent role of Bcl-3 in the liver, and our work suggests deletion of Bcl-3 greatly ameliorates TNF-induced liver injury, which provides a potential therapeutic target for various liver diseases." (PMID 34853447, 2022).
mammary adenocarcinomas (2 papers, 2022 to 2024). "Bcl-3 is expressed in mammary adenocarcinomas and can promote tumorigenesis and survival signaling and has a key role in tumor metastasis." (PMID 35681213, 2022). "Lastly, a reduced incidence of bcl-3−/− mammary adenocarcinomas versus squamous lesions indicates that Bcl-3 supports the progression of epithelial but not metaplastic cancers." (PMID 35681213, 2022). "Overall these results demonstrate that Bcl-3 is an important regulator of normal mammary gland biology and contributes to the development and/or progression of mammary adenocarcinoma, at least in part, as a consequence Bcl-2 regulation." (PMID 35681213, 2022). "Overall these results support a role for Bcl-3 in the regulation of non-canonical and canonical NF-κB activity and Bcl-2 expression in mammary adenocarcinomas such that its absence results in preferential expansion of squamous tumors lacking both NF-κB activity and Bcl-2 expression." (PMID 35681213, 2022).
myocardial ischemia (2 papers, 2017 to 2021). A disorder of cardiac function caused by insufficient blood flow to the muscle tissue of the heart. "In our study, the expression level of Bcl-3 was markedly up-regulated by CIRBP overexpression, which might be another explanation for the effect of CIRBP on proliferation and apoptosis of H9C2 cells with myocardial ischemia." (PMID 28355355, 2017).
non-Hodgkin lymphoma (2 papers, 2019 to 2022). Distinct from Hodgkin lymphoma both morphologically and biologically, non-Hodgkin lymphoma (NHL) is characterized by the absence of Reed-Sternberg cells, can occur at any age, and usually presents as a localized or generalized lymphadenopathy associated with fever and weight loss.
parasitic infection (2 papers, 2016 to 2024). "Bcl-3 dysregulation can be observed in a number of autoimmune pathologies, and Bcl3-deficient animals are more susceptible to bacterial and parasitic infection." (PMID 27023613, 2016).
preeclampsia (2 papers, 2023). Preeclampsia is a hypertensive disorder of pregnancy that is characterized by new-onset hypertension with proteinuria presenting after 20 weeks of gestation, and depending on mild or severe forms may initially present with severe headache, visual disturbances, and hyperreflexia. "BCL-3 modulates the expression of specific genes to participate in suppression of the innate immune response, but overexpression of BCL-3 in human placentas is related to severe early-onset preeclampsia." (PMID 36978599, 2023). "BCL-3 regulates the expression of TNF-α to inhibit the innate immune response; however, the overexpression of BCL-3 is associated with early-onset preeclampsia." (PMID 37505866, 2023).